IL6 (interleukin 6)
Diseases named in the same sentence as IL6 in open-access papers (continued):
Sharing a sentence is not in itself a finding about the gene and the disease.
Allergy (170 papers, 2002 to 2026). An allergy is an immune response or reaction to substances that are usually not harmful. "Conversely, polymorphisms resulting in elevated IL-6 levels or signaling have greater risk of allergy, proliferative diabetic retinopathy and other immune-related pathologies." (PMID 39114667, 2024). "Increased propensity of Th2 cells and allergy symptoms are brought on by loss-of-function mutations in IL-6 signaling, especially the IL-6 receptor." (PMID 38835658, 2024). "IL-6 rs1800795G allele (in particular GG genotype) was increased in the allergy patient group as well as IL-10 rs1800896AA genotype and IL-10RB rs2834167G/* positive genotypes." (PMID 39202464, 2024). "Given that these vaccines can cause a cytokine storm and allergic reactions post vaccination, it is crucial to consider corticosteroids and measure IL-6 levels for effective management." (PMID 39452475, 2024). "A comprehensive meta-analysis study examined the potential correlation between the IL-6 gene (− 174G/C) polymorphism and allergic diseases in a sample of 1282 patients with allergic ailments and 1902 control subjects." (PMID 38388670, 2024). "Conversely, in Asian populations, the IL-6 gene (− 174G/C) polymorphism was associated with an increased risk of overall allergic diseases in dominant, allele, and homozygote comparisons." (PMID 38388670, 2024). "Among Caucasians, the IL-6 gene (− 174G/C) polymorphism was correlated with a reduced risk of overall allergic diseases in dominant, allele, and heterozygote comparisons." (PMID 38388670, 2024). "It was found that HMGB1, HMGB2, IL-6, IL-1β, and family history of allergy were the risk factors for AR." (PMID 37713866, 2023). "IL-6 rs1800795 is associated with allergic disease susceptibility among Asians and Caucasians in opposite directions." (PMID 37558924, 2023). "The association between allergic diseases and poor oral health is related to increased levels of inflammatory cytokines, such as interleukin (IL)-1β, IL-6, and tumor necrosis factor-α." (PMID 36833618, 2023). "Results of pooled ORs in the meta-analysis of the association between IL-6 gene polymorphisms and each allergic disease." (PMID 35368692, 2022). "Many studies aimed to evaluate the relationship between the IL-6 polymorphisms and allergic diseases risk in different populations." (PMID 35368692, 2022). "Recent studies demonstrated the association between IL-6 gene polymorphisms and allergic diseases risk." (PMID 35368692, 2022). "Results of pooled ORs in the meta-analysis of the association between IL-6 gene polymorphisms and overall allergic disease." (PMID 35368692, 2022). "Stratified by age, IL-6 rs1800795 was negatively related to susceptibilities of overall allergic diseases in both adults and children." (PMID 35368692, 2022). "In animal studies, BPS was associated with cytokines related to allergic reactions, such as IL-6, IL12a, and interferon c." (PMID 34822682, 2021). "The frequency distribution depicted strong association of IL-6 174-G/C polymorphism with allergy and the sub-groups except dermatitis group that represented a weak association with the given polymorphism." (PMID 31251775, 2019). "IL-6 is a crucial immune system regulator that is involved in the survival and maturation of mast cells; thereby it is associated with the prognosis of allergy." (PMID 31251775, 2019). "The dual remission observed in this case suggests that interleukin-6 (IL-6) inhibition may modulate shared immunological pathways underlying autoimmune and allergic diseases." (PMID 40130131, 2025). "Some studies suggest that insufficient sleep can alter levels of inflammatory cytokines such as interleukin (IL)-1β, IL-4, IL-6, and IL-10, which may promote allergic reactions and elevate the risk of developing AR." (PMID 40283018, 2025). "In addition to its role in autoinflammatory diseases, IL-6 has been implicated in the pathogenesis of allergic diseases." (PMID 40130131, 2025).
Allergy (continued). "Nevertheless, to the author’s knowledge, this is the first piece of work that establishes a connection between TGF-β/Smad pathway, IL-1β and IL-6 levels, metabolic pathways, the type of allergy, metabolic dysregulations, and the risk of cancer within a unified framework." (PMID 38629073, 2024). "The role of IL-6 gene polymorphisms in allergic diseases appears to be relevant." (PMID 39202464, 2024). "Finally, we found that HMGB1, HMGB2, IL-6, IL-1β, and family history of allergy were the risk factors for AR." (PMID 37713866, 2023). "Leucine (Leu) and Arginine (Arg) not only significantly enhance the expression of the major histocompatibility complex (MHC) on the surface of dendritic cells but also increase the relative gene expression of Interleukin-6 (IL-6) and Interleukin-12 (IL-12), which cause food allergic reactions." (PMID 36770908, 2023). "When degranulation occurs, histamine and inflammatory cytokines, such as IL-6, are released, causing severe itching, redness of the skin, vasodilation, and increased vascular permeability, which is known to play a central role in allergic reactions." (PMID 35457288, 2022). "In addition, IL-6 rs1800795 polymorphism was associated with allergic diseases susceptibility among Asians." (PMID 35368692, 2022). "Based on these, we hypothesized that rs1800795 polymorphism could affect the differentiation of Th1 and Th17 cells by affecting the expression of IL-6, thereby affecting the risk of allergic diseases." (PMID 35368692, 2022). "Hence, the purpose of the present research lies at generalizing the existing proof to clarify the exact association between IL-6 gene polymorphisms and the risk of allergic diseases." (PMID 35368692, 2022). "Therefore, our meta-analysis was the first study on genetic associations of IL-6 rs1800795, rs1800796, and rs1800797 polymorphisms with allergic diseases." (PMID 35368692, 2022). "Through the inclusion of studies on three kinds of allergic diseases and three IL-6 polymorphisms, we explored whether the IL-6 SNPs were shared risk variants of these allergic diseases." (PMID 35368692, 2022). "Second, environmental factors might impact the association between IL-6 polymorphisms and allergic diseases as well." (PMID 35368692, 2022). "Thus, we performed this meta-analysis based on the accumulating evidence to estimate the link between IL-6 gene polymorphisms and allergic diseases risk (including allergic rhinitis, allergic asthma, and atopic dermatitis)." (PMID 35368692, 2022). "Considering the different pathogenic and epigenetic potential factors of the three allergic diseases, the relationship between IL-6 gene polymorphisms and the risk of each disease may be different." (PMID 35368692, 2022). "Additionally, the study found that the IL-6 (− 174G/C) variant significantly correlates with a lower risk of childhood allergic diseases across different age groups, observed in multiple comparisons, including dominant, allele, heterozygote, and homozygote comparisons." (PMID 38388670, 2024). "Moreover, differences in ethnicity and age could affect genetic association between IL6 rs1800795 polymorphism and allergic diseases." (PMID 35368692, 2022). "Besides these, we carried out isolated meta-analyses for each allergic disease to check the impact of IL-6 SNPs on each disease and also to identify whether IL-6 SNPs were shared risk variants of allergic diseases." (PMID 35368692, 2022). "The results showed that Lp synergistic FOS significantly decreased clinical allergy scores, inhibited specific antibodies (IgE, IgG, and IgG1), IL-4, IL-6, and IL-17A levels, and increased IFN-γ and IL-10 levels." (PMID 39796399, 2025). "They found that the extract suppressed the release of mediators related to skin autoimmunity—IL-6 and IL-17C—and allergy—TSLP (thymic stromal lymphopoietin), IL-6, CCL26 (chemokine (C-C motif) Ligand 26), and MMP-9 (matrix metalloproteinase)." (PMID 40649262, 2025).
Allergy (continued). "Allergy symptom scoring (gastrointestinal, respiratory, skin, and systemic allergy reflections); inflammatory factors (TNFα/IL-1β/IL-6/IL-10); antibodies (IgE/IgG2); efficacy in eczema reduction." (PMID 40529417, 2025). "In contrast, our case presents a unique scenario with dual remission and concurrent resolution of autoimmune and allergic diseases with IL-6 inhibition." (PMID 40130131, 2025). "Proinflammatory cytokines with high importance in developing allergic reactions: IL-1β, IL-6, TNF-α, TGF-β, and GM-CSF were selected for the study." (PMID 39881795, 2025). "Regarding the results we presented here, they can be viewed as quite interesting since, in the context of allergies, inhibiting IL-6 levels is presumed to be advantageous." (PMID 38541700, 2024). "This is interesting as an in vitro study has shown that synthesis of lactose in lactating mammary epithelial cells is inhibited by pro-inflammatory cytokines TNF-α, IL-1β and IL-6, all of which play roles in allergy." (PMID 39458508, 2024). "To identify these neuromodulators, we exposed (24h) cultured JNC neurons to various allergy driving cytokines, inflammatory lipids, and neurotrophins, and used transcription changes to Npy1r, Sting1, Bdnf, and Il6 as proxies for an AAI-like signature." (PMID 39345572, 2024). "Individuals with DOCK8-deficiency have a high incidence of allergic diseases and eczema, hyper IgE, eosinophilia, and a profound type-2 CD4+ T helper cell (Th2) bias, leading to IL-6 overexpression." (PMID 39044832, 2024). "Investigating a connection between IL-6 gene variations and specific allergic conditions is crucial due to the contribution of various factors and epigenetic influences on different allergic diseases." (PMID 38388670, 2024). "In comparison to the allergy cohort, we found differences especially for the expression of IL-6 and IFN γ." (PMID 38098024, 2023). "Interleukin 6 (IL-6), a pleiotropic cytokine capable of both inflammatory and anti-inflammatory responses, can elicit chronic inflammation and allergy in the lungs." (PMID 37373252, 2023). "IL-6 acts in innate immunity, allergy and on the T helper cell differentiation, explaining the reduced susceptibility to SARS-CoV-2." (PMID 37997984, 2023). "Microorganisms modulate immune responses, including the production of cytokines such as IL-6 and IL-10, to affect the development of immune reactions and protection against allergic diseases." (PMID 37978564, 2023). "Apart from the release of preformed mediators, the release of de novo synthesized inflammatory mediators such as TNF-α, IL-6, IL-8, and IL-4 by activated MC in a prolonged allergic reaction was well-reported in previous studies." (PMID 37667314, 2023). "Cytokines (IL6) in adipose tissue were reported in overweight and obese subjects, leading to impaired immune tolerance against allergic diseases." (PMID 38125695, 2023). "Increased IL-6 in AR + ACD patients is possibly an intermediate responder along with the allergy march from ACD to ACD + AR." (PMID 35148790, 2022). "HVE inhibited the release of mediators involved in skin autoimmunity (IL-6 and IL-17C) and allergy (TSLP, IL-6, CCL26, and MMP-9) with a concentration-dependent fashion (IC50s < 25 μg/mL)." (PMID 36012541, 2022). "The production of IgE induced by the allergen is the main process leading to an allergic reaction, and IL-6 and IL-8 can stimulate the secretion of IgE by promoting the differentiation of acidic granulocytes." (PMID 36045965, 2022). "IL6 is also involved in the pathophysiology of allergic diseases, and high levels of IL-6 in the blood promote the release of allergic mediators and exacerbate allergic rhinitis." (PMID 36012469, 2022). "In contrast, Th2 cells, which produce IL-4, IL-5, IL-6, IL-9, IL-10, and IL-13, induce strong antibody responses by B cells, induce eosinophil activation, and are responsible for allergic reactions." (PMID 35646978, 2022).
Allergy (continued). "Although infection is the primary cause of fever, endogenous heat sources such as IL-1β, TNF, IL-6, and PTGS2-induced prostaglandins also act on the thermoregulatory centers of allergic diseases." (PMID 35855823, 2022). "PMA/A23187 acts on mast cells and induces them to produce IL-1β, IL-6, TSLP, and TNF-α, causing allergy-related inflammation." (PMID 34681651, 2021). "As a primary activator of Th2 cells, IL-6 leads to the secretion of IL-4 and IL-13, promoting the Th2 immune response, which is considered pivotal in the pathogenesis of allergy." (PMID 33525403, 2021). "An IL6-allergic disease relationship was established by Pharos, with 79 supporting PubMed publications contributed by OmniCorp." (PMID 34283031, 2021). "The half-life, toxicity, and unwanted properties like in SARS-CoV-2 cases such as IL-6 inducing potential, immunosuppressive property, hemolysis, and allergy must also be checked." (PMID 33133071, 2020). "Levels of allergy mediating cytokines, IL-6, IL-10, and IFN-γ, as well as chemokines RANTES and TARC were also reduced upon SHE administration." (PMID 32824648, 2020). "In contrast, Th2 cells mainly secrete IL-4, IL-3, IL-6, and IL-10 to stimulate the proliferation of activated B cells, to produce antibodies, and to participate in humoral immune-related or allergic diseases." (PMID 33659270, 2020). "The results signified the role of SOCS3 in allergic reaction as it was elevated in different types of allergies under the influence of IL-6 serum levels." (PMID 31251775, 2019). "The given study focuses on the assessment of crosstalk between SOCS3 and IL-6 to unravel the molecular significance of SOCS3 and IL-6 in the diagnosis and prognosis of allergy." (PMID 31251775, 2019). "IgE-mediated inflammation is regulated by the cascade of defense related signaling molecules including interleukin-6 (IL-6) that plays pivotal role in the survival and maturation of mast cells during an allergic reaction." (PMID 31251775, 2019). "In human macrophages, DEHP treatment increases the production of inflammatory cytokines, such as TNF-α, IL-1β, IL-8, and IL-6, which induces the inflammatory response during allergic reactions." (PMID 31297340, 2019). "IL-6 starts in the inflammation process and takes part in the erythropoiesis and many allergic reactions." (PMID 30032408, 2018). "Release of IL-4 primarily regulates hyper-production of IgE, and expression of TNF-α and IL-6 stimulate the synthesis of acute phase response protein, which attenuates secretion of IgE and disruption of skin barrier function during allergic reactions." (PMID 28358324, 2017). "Our results were interesting in that IL-6 and IL-8 were related to physiological stress and childhood allergies." (PMID 26819847, 2016). "In allergic reactions, 5-HT and IL-6 were found to be the apparently changed physiological indicators which were different from those of anaphylactoid reactions and inflammatory reactions." (PMID 27754330, 2016). "The specific release of preformed IL-6 from peripheral blood mononuclear cells (PBMC) after 20 minutes incubation with 0.15–0.5 μM of pure drugs was measured in two groups of drug-allergy suspected donors and respective controls." (PMID 25709746, 2015). "The levels of pro-inflammatory cytokines (IL-1β, IL-6, TNF), anti-inflammatory cytokine (IL-10), Th2-type cytokines associated with allergy (IL-4, IL-13, IL-33) and Th1-type cytokine (IFN-γ) were analysed from the treated skin sites of all groups." (PMID 25123235, 2014). "Th2 cells mainly secrete IL-4, IL-5, IL-6 and IL-10, which are involved in humoral immune and allergic reactions." (PMID 24520300, 2014). "Immune regulatory Th2 cytokines, such as IL-4, IL-6, and IL-10, which favor humoral immunity, mediate allergic diseases, control chronic infections, and promote adaptive immunity." (PMID 25264680, 2014).
Allergy (continued). "Meanwhile, C44 is more suitable than C48 in the context of allergic diseases, based on its attenuated Th2 (IL-5, IL-6 and IL-10) potential." (PMID 23554802, 2013). "In patients with both types of allergy i.e. skin and rhinitis, there was a positive correlation of IL-5 with IL-10 and that of IL-6 with TNF α." (PMID 20616938, 2010). "More importantly, IL-6 has been reported to function both upstream and downstream of IL-17, constituting a positive feedback loop that promotes autoimmune and allergic diseases." (PMID 19907660, 2009). "IL-6 exacerbates allergic reactions by inducing the production of Th2-type cytokines." (PMID 40570726, 2025). "On this subject, finding the right balance in the levels of IL-6 inhibition is of paramount importance for the success of the therapeutic management of allergies, and its use at LD and ULD could be an effective and safe solution." (PMID 38541700, 2024). "Formal statistical analyses show that IL-6 rs1800795GG, IL-10RB rs2834167G positive genotypes, IL-13 rs1800925CC, CD23 rs2228137TT Klotho rs564481TT, might be risk factors for allergy." (PMID 39202464, 2024). "Furthermore, the activated NLRP3 inflammasome promotes the expression and regulation of various inflammatory factors, including IL-6, IL-17, and IL-33, participating in allergic disease development." (PMID 39131161, 2024). "According to the current knowledge, targeting IL-6 in the context of allergic diseases could be beneficial for patients suffering from atopic dermatitis." (PMID 38541700, 2024). "The findings revealed that, in the general population, there was no notable link between the IL-6 gene − 174G/C polymorphism and the overall risk of allergic diseases." (PMID 38388670, 2024). "In any case, other kinds of auxiliary lymphocytes could be involved, such as Th-17 and its main metabolites, IL-17, or IL-6, when an increase in allergic diseases is reported; thus, they might play a relevant role in the loss of interest in sex." (PMID 37123746, 2023). "In order to determine the inhibitory effect on de novo synthesized inflammatory mediators, including TNF-α, IL-6, IL-8, and IL-4 released during an allergic reaction, the HMC-1 cells were pre-treated with KHs for 1 h and followed by a 24 h of induction with PMACI." (PMID 37667314, 2023). "Additionally,the IL-6/JAK/STAT3 signalling pathway has been shown to be associated with mast cell degranulation and allergic reactions." (PMID 38045687, 2023). "Pathway analysis of the putative PDGF-BB-regulated genes showed that these had highly pleiotropic effects of potential relevance for allergies: B cell signaling, cell migration and proliferation, immune response, and cytokine-related pathways, for example, via IL-6, IL-7, IL-8, and IL-15 signaling." (PMID 35513850, 2022). "Furthermore, B cells activation and IgA and IgG1 secretion provoked by IL-6 and IL-10 lead to allergy symptoms reduction." (PMID 35812388, 2022). "Specifically, the results suggest that isopropanol might trigger an innate neuroimmune response that results in elevated levels of IL6, which then might trigger neurobehavioral symptoms of allergic disease." (PMID 34283031, 2021). "In addition, ROBOKOP identified publication support suggesting the involvement of IL6 in neuroimmune and neurobehavioral correlates of allergic disease." (PMID 34283031, 2021). "In addition, IL-6 can also increase the expression of IgE receptors (FcεRI) and the production of histamine, which is closely related to allergic reactions." (PMID 34361003, 2021). "Additionally, the administration of SHE inhibited the mRNA expression levels of allergy mediating cytokines, IL-6, IL-10, and IFN-γ in HDM/DNCB stimulated mice." (PMID 32824648, 2020). "Moreover, the association between GG and SOCS3 expression implied that SOCS3 expression is firmly regulated by IL-6 serum levels thereby making IL-6 as a potential candidate involved in the prognosis and pathogenesis of allergy." (PMID 31251775, 2019).